OR13C6P (olfactory receptor family 13 subfamily C member 6 pseudogene)
Description:
Odorant receptor.
Synonyms: OR37B
Gene: Unprocessed pseudogene on chromosome 9 (35,991,336 to 35,992,285, reverse strand). Ensembl gene ENSG00000179443.
Subcellular location: Cell membrane